CCL20 (C-C motif chemokine ligand 20)
Diseases named in the same sentence as CCL20 in open-access papers (continued):
Sharing a sentence is not in itself a finding about the gene and the disease.
breast tumor (8 papers, 2013 to 2025). "In contrast, malignant cells from primary breast tumors were enriched for genes associated with chemotaxis and immune regulation, including CCL20 and CXCL259,60." (PMID 40858590, 2025). "The ELAVL1 (the gene that encodes HuR) and CCL20 expression levels were both markedly increased in breast tumor tissues compared with normal breast tissues." (PMID 28851919, 2017). "Upregulation of Ccl19, Ccl20 and chemokine (C-X-C motif) receptor (Cxcr) 2 has also been associated with breast tumor growth and invasion, Cxcr2 particularly with angiogenic processes." (PMID 24156623, 2013). "Gene Expression Profiling Interactive Analysis 2 (GEPIA2) database showed that the expression of CCL20 was positively correlated with the expression of CD11b (a myeloid marker in human, p value = 6.8e-25, R = 0.31) in patients’ breast tumors." (PMID 36859354, 2023). "Although increases in FOXP3+ TILs infiltration and CCL20 expression have been revealed in several malignancies, their correlation in human breast tumors is as yet unclear." (PMID 31852159, 2019). "CCR4 is known to be down regulated on Tregs after their sensitization to CCL22 but other chemokine receptors, such as CCR6, which are expressed on these Tregs, which is interaction with CCL20 production by breast tumor cells." (PMID 24124553, 2013). "Thus, high CCL20 expression in primary breast tumours significantly reduces cumulative survival of the patients after tumour excision." (PMID 32601464, 2020).
depression (8 papers, 2018 to 2025). "Furthermore, STRING analysis underscored the shared roles of specific proteins, including EGFR, IL15, CCL2, and CCL20, in the context of air pollution-induced depression and anxiety, highlighting the involvement of immune-related processes and pathways." (PMID 40611827, 2025). "Our research suggests that the concurrent upregulation of CCL2 and CCL20 in response to air pollution may have a synergistic effect in promoting neuroinflammation, thereby mediating the relationship between air pollution and depression and anxiety." (PMID 40611827, 2025). "STRING analysis further underscored the shared roles of proteins IL15, C–C Motif Chemokine Ligand (CCL)−2 and CCL20 in the context of air pollution-induced depression and anxiety, potentially highlighting EGFR's critical role in depression." (PMID 40611827, 2025). "Positive correlations were observed between MIP-1α/CCL3, MIP-1β/CCL4, MCP-1/CCL2, MIP-3α/CCL20, RANTES/CCL5, Eotaxin/CCL11, and I-TAC/CXCL11 with high scores for anxiety (HARS) (p < 0.05) and for depression (HDRS) (p < 0.004)." (PMID 34863117, 2021).
experimental autoimmune encephalomyelitis (8 papers, 2013 to 2025). An autoimmune demyelinating disease of the central nervous system that is produced experimentally in animals by the injection of homogenized brain or spinal cord in Freund's adjuvant. "However, recent studies on experimental autoimmune encephalomyelitis involving CCL20-knock-out mice suggest that this signaling deficiency may be compensated by mechanisms of chemokine redundancy." (PMID 38674602, 2024). "The selective estrogen receptor modulator (SERM) raloxifene, for example, can elicit robust neuroprotection against experimental autoimmune encephalomyelitis, partially via an inhibitory action on NF-κB and CCL20, a chemokine involved in neuroinflammation." (PMID 25510908, 2014). "In conclusion, these data demonstrate that raloxifene provides robust neuroprotection against experimental autoimmune encephalomyelitis, partially via an inhibitory action on CCL20 expression and NF-κB pathways in reactive astrocytes." (PMID 24722370, 2014). "CCL20, as a sole ligand of CCR6 (C-C motif chemokine receptor 6), attracts lymphocytes, and the CCR6–CCL20 axis is important for the initiation of experimental autoimmune encephalomyelitis (EAE), by promoting the infiltration of IL-17 cells to CNS via the choroid plexus." (PMID 39125633, 2024). "Our results contribute to a better understanding of the critical roles of raloxifene in treating experimental autoimmune encephalomyelitis and uncover reactive astrocytes as a new target for the inhibitory action of estrogen receptors on chemokine CCL20 expression." (PMID 24722370, 2014).
fibrosis (8 papers, 2010 to 2025). the formation of excess fibrous connective tissue in an organ or tissue in a reparative or reactive process. "Mip-3α (CCL20) is another chemokine observed to increase in parallel with the severity of MASLD-associated fibrosis." (PMID 40794228, 2025). "NAFLD fibrosis is known to be associated with an increase in CCL20, an essential inflammatory mediator." (PMID 36950134, 2023). "We used microarray technology, a focused PCR-based array, and RNA sequencing to identify the C-C motif chemokine ligand 20 (CCL20) as a highly up-regulated transcript in NAFLD-associated fibrosis relative to normal liver histology." (PMID 29690903, 2018). "We then analyzed expression of CCL20 mRNA in an independent group of liver RNA samples with advanced fibrosis using quantitative PCR (QPCR)." (PMID 29690903, 2018). "Furthermore, it was reported that CCL20 is upregulated in hepatocytes upon injury and improves hepatic fibrosis by recruiting γδT cells in CCl4 mouse models." (PMID 37686029, 2023). "Increased expression of the chemokine CCL20, which belongs to a class of molecules that serve as chemoattractants for the infiltration of immune cells to the injured liver, was associated with NAFLD fibrosis." (PMID 29690903, 2018). "CCL20 protein levels in the serum were measured using ELISA in 183 patients including 106 with normal liver histology, 18 with grade 1 fibrosis, 18 with grade 2 fibrosis, 28 with grade 3 (bridging) fibrosis, and 13 with grade 4 fibrosis (cirrhosis)." (PMID 29690903, 2018). "The expression of S100A8, S100A9, S100A8/A9, CCL20, and IL-17, detected by ELISA, is significantly increased in NASH patients with fibrosis in comparison with controls." (PMID 26273651, 2015). "CCL20/CCR6 mRNA and protein expressions in PCA were compared to several clinicopathological factors such as TNM stages, age, lymphatic and vascular invasion or pre-existing conditions like cirrhosis or fibrosis." (PMID 20459729, 2010). "In the present study, we analyzed the expression of liver injury-related genes in patients with MASLD and could demonstrate a significant upregulation of IL-32 and CCL20 in MASH samples with progressed activity (intense steatosis and moderate-to-severe fibrosis)." (PMID 37686029, 2023). "With regards to other specific chemokines, CCL20, also known as macrophage inflammatory protein (MIP-3α), is a chemoattractant for immune cells recently shown to be transcriptionally upregulated in the livers of bariatric surgery patients with NASH-related fibrosis." (PMID 32730345, 2020).
skin inflammation (8 papers, 2016 to 2025). "Oral propionate and the HFD reduced mRNA expression of IL-17A, IL-17C, IL-17F, IL-22, IL-1β, IL-6, TNF-α, CXCL1, CXCL2, and CCL20 in imiquimod-induced dermatitis." (PMID 37762500, 2023). "Oral propionate decreased mRNA expression of IL-17A, IL-17C, IL-17F, IL-22, IL-6, IL-1β, TNF-α, CXCL1, and CCL20 in imiquimod-induced dermatitis in comparison between NDIS versus NDIP." (PMID 37762500, 2023). "Under these conditions, keratinocytes produced cytokines and chemokines, such as IL-8, IL-36γ, and CCL20, which recruit inflammatory cells and exacerbate skin inflammation." (PMID 28761880, 2017). "Additionally, Anxa1 regulates T cell activity in skin inflammation, and Ccl20 and Trp73 are involved in inflammatory responses." (PMID 38834629, 2024). "The HFD- or propionate-induced reduction in CXCL1/2 or CCL20 expression might result in the reduced infiltration of neutrophils or T cells/γδT cells in the imiquimod-induced dermatitis, respectively." (PMID 37762500, 2023). "Together, inflammatory mediators (IL-17 and CCL20) and SASP factors such as IL-1 and IL-6 function in a self-amplifying loop to induce alopecia and dermatitis in irradiated animals." (PMID 37237461, 2023). "Oral propionate reduced inflammatory infiltrates and epidermal Ki67+ cells and reduced mRNA levels of IL-17A, IL-17F, IL-17C, IL-22, IL-1β, IL-6, TNF-α, CXCL1, CCL20 and increased those of TGF-β1and IL-10 in imiquimod-indued dermatitis." (PMID 37762500, 2023). "In imiquimod-induced dermatitis, IL-17A, IL-17F, and IL-22 may be mostly derived from Th17 cells or γδT17 cells, while CXCL1, CXCL2, CCL20, and IL-17C may be mainly produced by epidermal keratinocytes." (PMID 37762500, 2023).
thyroid cancer (8 papers, 2018 to 2025). "The results of MR analysis showed that significant causal association between CCL20 [OR (95%CI), 0.763 (0.614–0.949), p = 0.02] and Malignant neoplasm of thyroid gland (finn-b-C3_THYROID_GLAND)." (PMID 38075694, 2023). "In thyroid cancer, CCL20/CCR6 promotes the invasion and migration of thyroid tumor cells via p65 NF-κB signaling." (PMID 30052635, 2018). "For example, the CCL20/CCR6 interaction enhanced the invasion and migration properties of thyroid cancer cells by activating NF-κB and inducing the expression and secretion of MMP-3." (PMID 36380313, 2022). "Several researchers have additionally demonstrated that four chemokines, CXCL1, CCL5, CCL20 and CCL21, biologically affect thyroid cancer cells by modulating inflammation and the immune microenvironment." (PMID 33345267, 2021). "At present, CCL2, CCL15, CCL20, CXCL1, CXCL8, CXCL12, and CXCL16 are the main chemokines showing a role in thyroid cancer." (PMID 29977225, 2018). "Studies taking into account the role of CCL15, C–X–C motif ligand 12, CXCL16, CXCL1, CCL20, and CCL2 in the context of thyroid cancer will be reviewed with particular emphasis on CXCL8." (PMID 29977225, 2018). "The roles of CCL20 and CCL28 in small intestinal and thyroid cancer remain insufficiently investigated, while our findings demonstrate their potential as protective factors, which might provide valuable insights for future research endeavors." (PMID 38075694, 2023). "Some recent published studies have demonstrated that CCL20 promoted cancer progression by some pathways such as by activating p38 pathway in laryngeal cancer, through PI3K pathway in LC and via NF-kappa B pathway in thyroid cancer." (PMID 37938151, 2023). "Cochrane’s Q test did not provide evidence of heterogeneity between CCL20 (p = 0.357) and thyroid cancer." (PMID 38075694, 2023).
tuberculosis (8 papers, 2015 to 2026). A chronic, recurrent infection caused by the bacterium Mycobacterium tuberculosis. "In association with this, the expression pattern of many STAT-1 mediated proinflammatory pathway genes, including Cxcl10 (IP-10) and Ccl20 that are considered biomarkers of active Tb disease, were also downregulated in the ΔbfrB vaccinated mice lungs." (PMID 26339659, 2015). "Furthermore, the expression of CCL20, CXCL8 and CXCL2 has been implicated in the pathogenesis of tuberculosis." (PMID 33057074, 2020). "However, the exact role of CCL20 in tuberculosis remains to be clarified." (PMID 33057074, 2020).
alcoholic hepatitis (7 papers, 2015 to 2025). Acute hepatitis resulting from ingestion of alcohol. "CCL20 has been described to substantially augment inflammation and fibrogenesis in patients suffering from alcoholic hepatitis." (PMID 37686029, 2023). "Ccl20 and Cxcl1 mediate LPS-induced liver injury and are potential drivers of inflammation and fibrosis in alcoholic hepatitis." (PMID 34684425, 2021). "It has been reported that CCL-20 levels are significantly increased in various chronic liver diseases, such as alcoholic hepatitis and non-alcoholic fatty liver disease (NAFLD), and that CCL-20 triggers both inflammation and fibrosis in the liver." (PMID 41157623, 2025). "In contrast to human data where Ccl2, Ccl3, Ccl20 and Cxcl10 transcripts were significantly changed in alcoholic hepatitis compared to healthy control, none of these statistically significant changes were found in the murine models." (PMID 32051453, 2020).
co-infection (7 papers, 2016 to 2025). "Specifically, production of key proinflammatory cytokines (e.g., IL-1α and IL-1β), chemokines (e.g., CCL20 and CXCL8), and VEGFA was markedly downregulated during co-infection with either HCMV variant, reflecting the known synergistic interference between the two pathogens." (PMID 40980889, 2025). "Protein-protein interaction network analysis further delineated pathogen-specific hubs: inflammatory mediators (CXCL8, CCL20, IL6) in the E group, molecular chaperones (CCT5, RUVBL1/2) in the S group, and a distinctive IL6-FBL-centered network in co-infection." (PMID 40771952, 2025). "Co-infection of monocytes with PRRSV-2 strain IAF-Klop and S. suis led to synergistic effects on the expressions of IL-6, CCL5, and TNF-α, and additive effects on productions of CCL4, CCL14, CCL20, IL-15, and PTGS2 (COX-2)." (PMID 38547254, 2024).
endometriosis (7 papers, 2019 to 2023). The growth of functional endometrial tissue in anatomic sites outside the uterine body. "Our data indicated that CCL20-NAb treatment could ameliorate the loss in body weight caused by endometriosis lesions." (PMID 35841069, 2022). "Th17 cells express CCR6 (C-C Motif Chemokine Receptor 6), a receptor for the CCL20 (C-C Motif Chemokine Ligand 20) ligand that is produced by endometriosis stromal cells and has a chemotactic effect on Th17 cells." (PMID 37446108, 2023). "The suppression effect of CCL20-NAb on endometriosis lesions in vivo was demonstrated in mice models." (PMID 35841069, 2022). "Elevated CCL20 concentrations in the peritoneal fluid from endometriosis patients also recruit more Treg cells, leading to an increased proportion of Treg cells in the peritoneal fluid, thereby promoting the progression of endometriosis." (PMID 35841069, 2022). "The in vivo suppressive effect of CCL20/CCR6 axis inhibitors on endometriosis lesions was also demonstrated in mice models." (PMID 35841069, 2022). "The misdiagnosed patients with endometriosis demonstrated low serum CCL20 levels, similar to those in other benign cases, but showed remarkably high CA125 levels." (PMID 36387204, 2022). "Our study revealed the potential usefulness of CCL20 level as a biomarker for diagnosing early-stage OC with endometriosis differentiation." (PMID 36387204, 2022). "Since the mechanism by which macrophage-involved immune dysfunction contributes to endometriosis progression is imperfect, investigations of the CCL20/CCR6 axis in endometriosis are of interest." (PMID 35841069, 2022). "In this study, we demonstrated for the first time that macrophages facilitated endometriosis progression via the CCL20/CCR6 axis." (PMID 35841069, 2022). "Recently, some studies have explored the role of the CCL20/CCR6 axis in immunological interactions in endometriosis and examined its existence in ectopic tissues." (PMID 35841069, 2022). "Of interest, the CCL20 level (pg/ml) in endometriosis (24.86 [9.74–35.00]) was comparable with that in other benign cases (32.12 [14.33-40.20]) and significantly decreased compared with that in malignant cases (47.47 [23.69–93.30]), with a p-value of 0.019." (PMID 36387204, 2022). "This information suggests that increased concentration of CCL20 in the peritoneal fluid of women with endometriosis is at least partially due to increased expression of this chemokine by endometriotic cells." (PMID 34501240, 2021). "The evaluation of chemokines showed that the peritoneal fluid from patients with endometriosis displayed significantly higher concentrations of CCL20, CXCL8, CXCL9, and CXCL10." (PMID 34501240, 2021). "We also reported that the peritoneal fluid of patients with endometriosis showed significantly increased concentrations of CCL20, CXCL9, and CXCL10." (PMID 34501240, 2021). "The role of CCL20 as a chemokine responsible for the attraction of Treg cells by the peritoneal fluid of women with endometriosis was further confirmed in experiments with specific CCL20 neutralizing antibodies." (PMID 34501240, 2021). "Endometriosis was also associated with elevated concentrations of IL-6, IL-10, and TGF-β1/2 as well as CCL20, CXCL8, CXCL9, and CXCL10." (PMID 34501240, 2021). "The inflammatory milieu of the tissue may present increased CCL20 expression and, consequently, increase Th17 migration to the endometriotic tissue and development of endometriosis by pro-inflammatory cytokines secreted by those cells." (PMID 37092451, 2023). "Finally, the suppressive effect of CCL20-NAb on endometriosis lesions in vivo was demonstrated in mice models." (PMID 35841069, 2022). "Furthermore, we found that the peritoneal fluid from women with endometriosis displays chemotactic activity toward Treg cells and that this activity at least partially depends on CCL20." (PMID 34501240, 2021).
endometriosis (continued). "Besides, the Th17 cell subset has a role in endometriosis, mediated by secretion of IL-17 resulting in the secretion of chemokine (C-C motif) ligand 20 (CCL20; also known as macrophage inflammatory protein-3, MIP3A) by endometriotic cells." (PMID 32063886, 2019). "Interestingly, CCR6 is also expressed by Th17 cells and, indeed, CCL20 may also play a role in chemotaxis and activation of these cells in the course of endometriosis." (PMID 34501240, 2021). "CCL20 may be expressed in a variety of tissues and is involved in many pathological conditions including autoimmune disorders and cancer; however, a mechanism responsible for an increased concentration of CCL20 in the peritoneal fluid of women with endometriosis remains to be elucidated." (PMID 34501240, 2021). "Endometriosis is a chronic inflammatory gynecological disorder, and the CCR6/CCL20 system seems to be involved with the disease pathology." (PMID 37092451, 2023). "Our team has previously discovered that the CCL20/CCR6 signaling axis mediated by macrophages can promote the proliferation and migration of ESCs by blocking autophagic flux in endometriosis." (PMID 37816731, 2023). "By contrast, the serum CCL20 levels in premenopausal women have been reported to be lower in those with endometriosis than in those without endometriosis." (PMID 36387204, 2022). "Our results indicate the potential of usefulness of CCL20 level as a biomarker to differentiate endometriosis in the setting of ovarian tumors with elevated CA125 levels, which can reduce the false positivity rate from 41.11% in preoperative diagnosis to 15.56% at the optimal cutoff value of CCL20." (PMID 36387204, 2022).
head and neck squamous cell carcinoma (7 papers, 2020 to 2025). A squamous cell carcinoma that arises from any of the following anatomic sites: lip and oral cavity, nasal cavity, paranasal sinuses, pharynx, larynx, and salivary glands. "B. breve lw01 administration suppresses head and neck squamous cell carcinoma growth in mice, mediated by the upregulation of CCL20, which is associated with increased migration of CD11c DCs to ileal villi and tumor microenvironment via upregulation of IL-12137." (PMID 38055306, 2023). "The study found that treating head and neck squamous cell carcinoma (HNSCC) with radiation promoted CCL20 expression in HNSCC which in turn facilitated Tregs accumulating leading radiation resistance and tumor growth." (PMID 39985603, 2025). "Furthermore, a study on a mouse model of head and neck squamous cell carcinoma demonstrated that high-dose radiotherapy induced tumor cells to secrete the chemokine CCL20, which could enhance Tregs to infiltrate into the tumor tissue via the CCR6-CCL20 axis and exert their immunosuppressive effects." (PMID 38162672, 2023).